PRRT1B (proline rich transmembrane protein 1B)
Synonyms: IFITMD8; DSPD2
Gene: Protein-coding gene on chromosome 9 (131,545,520 to 131,560,618, forward strand). Ensembl gene ENSG00000283526.
Subcellular location: Membrane
Gene Ontology:
Cellular component: membrane
Homologues: Orthologues: chimpanzee PRRT1B (99% identical), macaque PRRT1B (94% identical), dog PRRT1B (73% identical), mouse Prrt1b (70% identical), pig PRRT1B (69% identical), rat Prrt1b (69% identical), rabbit PRRT1B (66% identical), guinea pig PRRT1B (57% identical), tropical clawed frog prrt1b (37% identical). Paralogues in human: PRRT1 (24% identical), PRRT2 (20% identical), TRARG1 (12% identical), TMEM233 (9% identical).